CD163 (CD163 molecule)
Diseases named in the same sentence as CD163 in open-access papers (continued):
Sharing a sentence is not in itself a finding about the gene and the disease.
tumor (continued). "Interestingly, an opposite effect was observed in the hearts: the M1 marker decreased while the M2 markers (CD206, Arg1 and CD163) increased in TAC-operated, PyMT-bearing mice compared to non-tumor-bearing mice." (PMID 37508517, 2023). "The results revealed that SNHG17 was highly expressed in tumor tissues and positively correlated with the level of TAM markers CD163, CD206, and IL-10, implying that SNHG17 not only played an essential role in the malignant progression of PDAC but was also closely associated with TAMs." (PMID 38098044, 2023). "Finally, of the neoadjuvant gem-RT group, there was a higher ratio of CD163+ macrophages compared to CD8 cells in the tumor tissue, suggesting a more immune suppressive profile in the tumor tissue." (PMID 37587309, 2023). "M2‐TAMs are tumor‐promoting macrophages and showed high expression of MRC1, CD163, MARCO, and MAF." (PMID 36529697, 2023). "After 6 weeks, subcutaneous tumours were harvested for IHC of POSTN, F4/80, and CD163." (PMID 37199594, 2023). "Indeed, a salient finding is that MDSCs based on flow cytometrical analysis and immunosuppressive CD163+ (i.e. M2-polarized) TAMs based on immunohistochemistry are not affected by eMSC treatment and remain abundant in the TME, even upon tumor growth reduction." (PMID 37928528, 2023). "In addition, we sought to visualize epithelial cells, M1 and M2 macrophages in the tumor microenvironment with PAN‐CK, CD80, and CD163 specific antibodies as the biomarkers." (PMID 35789544, 2023). "CD163+ cell density in the tumour compartment (p = 0.0067), but not in stroma (p = 0.17), was associated with worse OS." (PMID 37965317, 2023). "In the correlation analysis, BLR and SLR showed significant positive correlations with the degree of CD163 cell and CD8 cell infiltration in the tumor tissue, respectively, and both BLR and SLR were significant predictors of RFS after adjusting for age, sex, TNM stage, and tumor SUV." (PMID 36983926, 2023). "TAMs expressed more CD163 when co-cultured with tumor cells, regardless of CIITA expression, than when grown in monoculture (p = 0.01)." (PMID 38201622, 2023). "IOPN tumor cells presented an activated PD-1/PD-L1 axis and a surrounding microenvironment characterized by a larger number of B cells than T cells (p < 0.001) and CD68+/CD163+ macrophages, mainly located within the tumor." (PMID 37086293, 2023). "However, the low-grade group showed significantly more CD68+ macrophages, including CD68+, CD68+CD163-, CD68+CD163+, CD68+PD-1-, CD68+PD-1+, CD68+PD-L1-, and CD68+PD-L1+ cells, in both the tumor and total region than the high-grade group." (PMID 38023213, 2023). "In addition, monocyte/macrophage markers (CD14, CD68, and CD163) were also lower in the tumor core of liver metastases, but CD14 and CD163 were more abundant in peritumoral regions of liver metastases than lung or peritoneal metastases." (PMID 37768208, 2023). "LAIR-1 was multiplexed with lymphocyte markers (CD45RA, CD4, CD8, CD20, CD56), myeloid monocyte markers (CD14, CD68, CD163 for macrophages and CD66b for neutrophils), fibroblast marker (SMA), hematopoietic progenitor cells (HPC, CD34) and tumor marker (pan CK)." (PMID 36960400, 2023). "Clusters with a higher CD163 expression rate compared to CD68 were only observed in blood samples from tumor patients, but not in TIL." (PMID 38322012, 2023). "CD163+PDL1+ macrophages were markedly increased in THRLBCL cases, which may represent alternative activation of macrophages with tumour-promoting immuno-suppressive function via the PD1:PDL1 immune checkpoint axis." (PMID 37854674, 2023). "However, these samples observed different stromal and tumor enrichments for CD4+ T cells, cDC1s, and XCR1+CD163+ cells compared to CRC1." (PMID 37731497, 2023).
tumor (continued). "Indeed, tumor tissues were enriched in immunosuppressive M2 macrophage (CD163+) in both areas, while CD3+T cells were prevalent inside the tumor core, but lower than CD163+ cells, explaining the suppressive effect of TAM on T cells." (PMID 37584750, 2023). "Four macrophage subclusters were annotated, including a CD14+MSR1+CD163-cluster (MA1) that were mainly found in samples collected from the primary tumor site (ovary) and thus not seen in our previous study." (PMID 38328306, 2023). "We next examined the significance of TGF-β in the pro-tumorigenic effects of macrophages by evaluating the expression of CD163 and interleukin-10 (IL-10) (M2 macrophage markers), as well as matrix metalloprotease 2 (MMP2), which are known to promote tumor progression." (PMID 36980788, 2023). "Tumor-associated macrophages (TAM) marked by CD68, CD163, CD4+ and CD8+ T cells, non-neoplastic B cells and CD21+ follicular dendritic cells (FDC) are the components of FL TME." (PMID 37373066, 2023). "CCL2, CCR2, CD163, and CD4 were all widely expressed in both CNB and resected tumor samples." (PMID 37208442, 2023). "Our present data shows that IL4I1 produced by MHCII+ CD163− TAMs does not prevent tumor control in our model." (PMID 37526660, 2023). "Across all tumours, the CD68+CD163+ macrophages constituted only 5% of the CD68+ macrophages and 23% of the CD163+ cells, but demonstrated substantial inter-patient heterogeneity with cell densities ranging from 0 to 1080 cells/mm2 of tumour tissue." (PMID 36724681, 2023). "These genes include markers of alternative macrophage polarization (Arg1, Cd163), monocyte chemoattractant Ccl6, and ligands for CCR2 (Ccl2, Ccl7, Ccl12) and CCR5/1 (Ccl3, CCl4, Ccl9) suggesting that F4/80+ cells in these tumours represent an increase in TAM2‐like myeloid cells." (PMID 35924447, 2023). "Furthermore, both CD163 and FPR1 played a vital and positive role in the tumor-promoting signal pathways in order to promote the development of HGSOC." (PMID 38115318, 2023). "To investigate the spatial contexture of the TME, we used a mIF panel in 95 tumours to focus on CD8+ T cells, FoxP3+ Treg cells, and CD163+ M2-macrophages, and single-stain IHC of PD-L1, which have been shown to influence therapy response and outcomes in OAC patient subgroups." (PMID 37965317, 2023). "In this exploratory study we identified that CD68+CD163+CD206neg M2 macrophages were the predominant macrophage subtype in CLM, predominantly located in the tumor periphery with relatively higher density than the tumor center supported by the cellular spatial analysis." (PMID 37637998, 2023). "Monocyte/macrophages within the 4-culture tumor spheroids were characterized by a higher expression of CD163, CD206, PD-L1, and CD40 than those in the non-cancerous spheroids suggesting their differentiation towards an immunosuppressive phenotype." (PMID 37519820, 2023). "We next validated that XCR1+CD163+ cell types could be found in other colorectal (CRC2) and kidney (KID1) tumor samples subjected to Cyclone." (PMID 37731497, 2023). "Third, we present spatial metrics that have not been used in other studies of CD163+ TAMs in the tumor microenvironment, although NND-based metrics have been investigated for CD8+ T cells in solid tumors in multiple reports." (PMID 35053472, 2022). "Tumor sections were used for βig-h3, CD8, and CD163 staining." (PMID 35455739, 2022). "In this regard, the co-culture had the strongest effect as did the myeloid cells monoculture (i.e., in the absence of tumor cells), with one modest exception being CD163 in THP-1 cells not showing a significant surface expression following Hsp27 exposure." (PMID 36140293, 2022). "To determine whether tumor exosomes can be taken up by macrophages, we first allowed differentiation of THP-1 cells into CD206+ and CD163+ macrophages with phorbol 12-myristate 13-acetate (PMA) treatment." (PMID 35086548, 2022).
tumor (continued). "SEMA3C modified the PD-L1 expression in tumor and immune cells and is correlated with the M2-like macrophage marker ARG1/CD163 expression, which could reshape the tumor microenvironment." (PMID 35785187, 2022). "We therefore repeated the analyses for HGG only; ascorbate content was not different between CD163 positive/negative HGGs (p = 0.53), whereas CD163 positive HGGs tended to have lower 5-hmC levels than CD163 negative tumours (p = 0.059)." (PMID 36050369, 2022). "We investigated the infiltration of tumor tissue by host T cells and microglia/macrophages using the well-established markers CD3, CD4, CD8 (column 3–5), CD11b, CD204, and CD163 (column 6–8)." (PMID 36358353, 2022). "As expected, tumors were immune cell rich and the retina on the side of the tumor had significantly higher numbers of immune cells (4.3 fold greater number of CD45+, 2.4 fold greater number of CD163+, 1.9 fold greater number of IBA1+) in comparison to the opposite side of the retina." (PMID 35986368, 2022). "Jamiyan and colleagues reported that infiltration of CD163+ TAMs, rather than CD68+, in both tumor stroma (TS) and tumor nests (TN) was associated with poor prognosis in patients with triple-negative breast cancer (TNBC)." (PMID 35053472, 2022). "Examination of lineage-specific marker expression revealed four principal clusters corresponding to tumor and glia (using the SOX2, OLIG2, GFAP markers), lymphoid cells (CD45, CD3, CD8, and CD4), myeloid cells (CD45, PU.1, CD163, CD68, and CD11b), and endothelial cells (CD31)." (PMID 35973991, 2022). "In addition, CD86 protein expression remarkably negatively correlated with tumour differentiation and tumour node metastasis (TNM) stage, while CD163 protein expression significantly positively correlated with tumour differentiation and tumour size." (PMID 34964155, 2022). "Expression levels of CD206 and CD163 were higher in the stroma of PDLIM2-positive than in PDLIM2-negative TNBC tumours, but these differences were not significant." (PMID 36531051, 2022). "In this study, PTX3 was further found to mediate the migration and inflammation‐resolving‐polarization of microglia in the tumor microenvironment of GBM, in which microglia had enhanced ability in migration and increased expression of CD163 under the stimulation of PTX3." (PMID 35855654, 2022). "Similarly, the only another significant correlation that was evidenced was between the eight tumor samples bearing a concomitant positive staining for CD68 and CD163 above 5%, the presence of GC and a worse OS and EFS (p = 0.0515 and p = 0.0372, respectively)." (PMID 35326631, 2022). "Due to the rather pro-tumoral TME in HNSCC, one could have suspected an increase in the expression of the M2 markers CD163 and CD206 after adding the tumor cells plus their corresponding SN to the unpolarized macrophages." (PMID 34665291, 2022). "In some cases, the presence of extratumoral CD163+cells was observed, in face of a non-infiltrated tumor." (PMID 35937296, 2022). "Interestingly, we also revealed an increase in the CD163 to CD68 ratio during the transition from IPN to invasive BTC, thereby highlighting the tumour-promoting role of M2 TAMs." (PMID 36068277, 2022). "However, in recent years, scholars have mostly focused their prognosis for patients on the impact of tumor cells or the tumor microenvironment, such as CD47 expression and CD163+ macrophages, cytokeratin-19 (CK-19), and tumor-infiltrating platelets." (PMID 36159473, 2022). "Despite the phenotypic diversity, TAMs often present the M2-like phenotype with the progression of tumor, expressing characteristic markers such as the mannose receptor (CD206) and hemoglobin scavenger receptor (CD163) and correlating with poor prognosis in several solid tumors." (PMID 36151545, 2022). "CD163, CD204, and CD206 are widely used to define TAM subpopulations with pro-tumor phenotypes." (PMID 35725444, 2022).
tumor (continued). "This can be explained by the high proportion of M2-type TAMs in the tumor, or by a lack of CD163 specificity." (PMID 36230752, 2022). "The M-IHC panel included CD68/CD163 (macrophage cocktail) and CK to determine whether ANXA2 staining was predominantly localized to tumor cells or macrophages." (PMID 36377658, 2022). "Here we found that LMR calculated in peripheral blood specifically and significantly correlated with stromal infiltration of CD68+ and CD163+ macrophages but not tumor tissue infiltration." (PMID 35958590, 2022). "Most importantly, the combined approaches of Bevacizumab and ipilimumab might synergistically increase the infiltration of CD163+ dendritic macrophages and CD8+ T Cells via tumor vasculatures." (PMID 36588679, 2022). "Along with TREM2, these cells were enriched for genes involved in lipid metabolism (APOE), immunosuppression (MARCO, CD163, CD81), and the complement cascade (C1QB), suggesting that TREM2 specifically marks a subset of tumor-specific immunosuppressive macrophages." (PMID 35746551, 2022). "The expression of multiple immune cells (CD8, Foxp3, CD68, CD163, CD20, CD11c, CD66b, CD56, PD-L1, INF-γ, Ki67 and VEGFR-2) in the tumor center (TC), tumor invasive front (< 150 μm from the tumor center, TF) and peritumoral region (≥ 150 μm from the tumor center, PT) was evaluated via comparison." (PMID 36195882, 2022). "In accordance with this study, our previous studies on CD163 have also shown positive expression in approximately 20% of CRC patients and its relationship to early local recurrence, short survival time, decreased apoptotic activity, and advanced tumor stage." (PMID 36551651, 2022). "Moreover, in HPV-positive tumors almost the 60 and 40% of CD163+ macrophages had CD8+ T lymphocytes within a 20 μm radius in the stroma and within the tumor areas, respectively, as compared to 20 and 10% in HPV-negative OPSCC." (PMID 36123711, 2022). "We then analyzed the associations between CXCL2 expression and classical macrophage phenotype markers of M0 (undifferentiated) (AIF1), M1 (anti-tumor) (IL12A, TNF, NOS2, PTGS2) and M2 (tumor-promoting) (IL10, CD163, TGFB1, CSF1R) in TCGA-LIHC cohort with Spearman’s rank correlation test." (PMID 36276119, 2022). "Neither did we observe any correlation between the AMC and CD68 or CD163 gene expression levels in the tumor tissue (p = 0.678 and p = 0.565, respectively) nor between the AMC and soluble CD163 levels in the serum (p = 0.998)." (PMID 36051040, 2022). "Moreover, many previous studies investigating the role M2 macrophages in the tumor microenvironment have characterized those macrophages based on expression of CD68 and CD163." (PMID 35503656, 2022). "A relationship between the ercDC from RCC tumor tissue and myeloid cells from chronic inflammatory kidney pathologies was previously suggested based on the triple marker staining of CD14, CD209 and CD163." (PMID 36291154, 2022). "We did not identify tumor cells or lymphocytes among these dense macrophage aggregates in the CD163 immunostained slides counterstained with hematoxylin." (PMID 35885058, 2022). "In addition, we discovered that the percentages of CD68+CD163+ and CD68+CD206+ cells in tumor tissue were significantly higher than in the adjacent healthy tissue (ANOVA, p < 0.05)." (PMID 36230558, 2022). "In canine lymphoma, tumor-infiltrating macrophages could be characterized as M1 and M2 according to iNOS, CD204 and CD163." (PMID 36311793, 2022). "The prognostic impact of the expression CD163, a receptor associated with TAM, and TYMP in stroma, respectively, tumor tissue is not yet established." (PMID 35567733, 2022). "Our analyses from the combined tumor regions (TC and IM) have demonstrated that the majority of patients’ tumors infiltrated by high numbers of CD8+ cells are also co-infiltrated by high densities of CD163+ and/or FoxP3+ cells." (PMID 36551693, 2022).
tumor (continued). "We validated the low expression of MARCO on HB TAMs using FISH, demonstrating the absence of MARCO on CD163+ macrophages in HB tumor tissues." (PMID 36008377, 2022). "CD163 expression increased in larger VS even without the involvement of the other tumor markers (p = 0.08)." (PMID 36139588, 2022). "This suggests that the infiltrating macrophages, independent of their polarization if determined by CD163 expression, increasingly express PD-L1 in tumor tissue." (PMID 35406584, 2022). "Given our data comparing the tumor penetration of an anti-PDL1 antibody versus St-PGA-OG-mUNO, anti-CD163 systems may also display lower tumor accumulation than St-PGA-OG-mUNO and OximUNO." (PMID 36923553, 2022). "Besides, the M2-like macrophages (F4/80+CD163+), MDSCs (CD11b+Gr-1+), and Tregs (CD3+CD4+FoxP3+) in the tumor regions were also analyzed by flow cytometry." (PMID 36319625, 2022). "Additionally, HPV-positive lymph node metastases revealed higher percentages of CD163+ TAM and FoxP3+ Treg cells detectable within a 20 μm radius from CTL in both stroma and tumor areas." (PMID 36123711, 2022). "Meanwhile, NTS presented positive relationships with CD163 and CD206, which are the molecular biomarkers of TAM-M2, reminding us that NTS may involve in polarization of tumour infiltrating macrophages to M2 subtype." (PMID 34141479, 2021). "In addition to the cluster of “macrophage-high” and “macrophage-low” tumors, a subset of tumors shows increased expression of CD68 and CD163 in the stroma, but low expression of CD163 in tumor nests and MHCII on tumor cells." (PMID 34200100, 2021). "While APRIL, BAFF, IL8 and MMP2 did not modulate with tumor stage, they were inversely related to the immune infiltrate level and CD163 tissue expression." (PMID 33846436, 2021). "In addition, there was a trend for a positive correlation of IL-8 and IP-10/CXCL10 with perivascular CD163+ cell infiltrates as well as a trend for a positive correlation of the percentage of CD163+ cells and MDC-1/CCL22 in the tumor core." (PMID 34654395, 2021). "The correlation between CD68 and CD163 expression was significant and strong in tumor nests (r = 0.764) and moderate in the stroma (r = 0.455) CD33 expression showed significant correlation only with CD163 (r = 0.651 in stroma and r = 0.605 in tumor nests)." (PMID 34200100, 2021). "It has been suggested that TAMs with an M2-like phenotype (markers CD163, CD204, and CD206) have a pro-tumor effect while M1-like TAMs (CD68, CD80, and CD86) may have an anti-tumor effect." (PMID 33882057, 2021). "CD163 is a marker of M2 macrophages, and CD31 is a marker of tumour blood vessels." (PMID 33742511, 2021). "We further examined and compared the dynamics and polarity of microglia/macrophages (Mφ) including resident Mφ (TMEM119 + Iba1+), M2-like Mφ (CD163 + Iba1+), and M1-like Mφ (iNOS + Iba1+) in the TME of the tumor control and dLGG–10, Lipo-DOX–2 and dLGG–10 + Lipo-DOX–2 group mice." (PMID 34439274, 2021). "In addition, myeloid cell densities in the tumor compartment were found to differ significantly based on differentiation grade (CD14 p = 0.001; CD68 p < 0.001; CD163 p < 0.001)." (PMID 34194435, 2021). "Based on bulk RNA data from the TCGA cohort, the highest levels of wild-type CYSLTR2 expression were observed in tumours with an inflammatory phenotype as shown by their immune gene expression signature (high expression of CD14, CD163 [monocytes/macrophages] and CD3D, CD8A [T cells])." (PMID 33588787, 2021). "In tumor nests, NE-low compared to NE-high tumors were associated with significantly increased densities of CD68+ (p = 0.048) and CD163+ cells (p = 0.024) in primary tumors, but not in LN metastases." (PMID 34200100, 2021). "Similarly, tamoxifen-resistant ER-positive and HER2-negative clinical samples had a higher density of CD163+ macrophage populations and increased expression of EGFR than tamoxifen-sensitive samples, which positively correlated with tumor size and metastasis." (PMID 33968034, 2021).